METTL4 (methyltransferase 4, N6-adenosine)
Description:
N(6)-adenine-specific methyltransferase that can methylate both RNAs and DNA. Acts as a N(6)- adenine-specific RNA methyltransferase by catalyzing formation of N6,2'-O-dimethyladenosine (m6A(m)) on internal positions of U2 small nuclear RNA (snRNA): methylates the 6th position of adenine residues with a pre-deposited 2'-O-methylation. Internal m6A(m) methylation of snRNAs regulates RNA splicing. Also able to act as a N(6)-adenine-specific DNA methyltransferase by mediating methylation of DNA on the 6th position of adenine (N(6)- methyladenosine). The existence of N(6)- methyladenosine (m6A) on DNA is however unclear in mammals, and additional evidences are required to confirm the role of the N(6)- adenine-specific DNA methyltransferase activity of METTL4 in vivo. Acts as a regulator of mitochondrial transcript levels and mitochondrial DNA (mtDNA) copy number by mediating mtDNA N(6)-methylation: m6A on mtDNA reduces transcription by repressing TFAM DNA-binding and bending. N(6)-methyladenosine deposition by METTL4 regulates Polycomb silencing by triggering ubiquitination and degradation of sensor proteins ASXL1 and MPND, leading to inactivation of the PR-DUB complex and subsequent preservation of Polycomb silencing (By similarity).
Synonyms: FLJ23017; HsT661
Tractability: PROTAC: ubiquitination databases record sites on it.
Gene: Protein-coding gene on chromosome 18 (2,537,525 to 2,571,509, reverse strand). Ensembl gene ENSG00000101574.
Subcellular location: Nucleus; Cytoplasm, cytosol; Mitochondrion matrix
Subcellular location (Human Protein Atlas): Mitochondria
Gene Ontology:
Molecular function: mRNA N6-methyladenosine dioxygenase activity; RNA methyltransferase activity; site-specific DNA-methyltransferase (adenine-specific) activity; U2 snRNA 2'-O-methyladenosine m6 methyltransferase activity; catalytic activity, acting on a nucleic acid; methyltransferase activity; nucleic acid binding; S-adenosylmethionine-dependent methyltransferase activity
Biological process: regulation of mitochondrial DNA replication; regulation of mitochondrial transcription; regulation of RNA splicing; RNA stabilization; snRNA (adenine-N6)-methylation; negative regulation of gene expression, epigenetic; regulation of RNA stability
Cellular component: cytosol; mitochondrial matrix; nucleus; RNA N6-methyladenosine methyltransferase complex
Genetic constraint (gnomAD): Loss-of-function variants: 27 observed, 33.04 expected, observed/expected ratio (o/e) 0.82, 90% interval 0.6 to 1.13. The upper end of that interval is the gene's LOEUF score, 1.13, which puts it in group 4 of 6, group 1 being the genes least tolerant of losing a copy. Missense variants: 394 observed, 427.49 expected, observed/expected ratio (o/e) 0.92, 90% interval 0.85 to 1. Synonymous variants: 127 observed, 146.95 expected, observed/expected ratio (o/e) 0.86, 90% interval 0.75 to 1.
Homologues: Orthologues: macaque METTL4 (97% identical), chimpanzee METTL4 (89% identical), pig METTL4 (85% identical), dog METTL4 (83% identical), rabbit METTL4 (77% identical), mouse Mettl4 (75% identical), rat Mettl4 (75% identical), guinea pig METTL4 (74% identical), tropical clawed frog mettl4 (48% identical), zebrafish mettl4 (40% identical), Drosophila melanogaster Mettl4 (21% identical), Caenorhabditis elegans damt-1 (21% identical).
Diseases named in the same sentence as METTL4 in open-access papers:
METTL4 is named in the same sentence as 34 diseases in open-access papers, as found by Europe PMC text mining. Sharing a sentence is not in itself a finding about the gene and the disease. The quoted sentences say what the papers report.
breast carcinoma (3 papers, 2021 to 2022). "LNC942, a lncRNA predominantly located in the cytoplasm, was reported to bind directly to a methyltransferase, METTL4, and promote METTL14‐mediated RNA m6A methylation in breast cancer." (PMID 35073459, 2022).
atherosclerosis (2 papers, 2025). A disease characterized by the build-up of fatty material and calcium deposition in the arterial wall resulting in partial or complete occlusion of the arterial lumen. "Pemetrexed, the first-reported METTL4 antagonist, is capable of reducing the progression of atherosclerosis." (PMID 40225569, 2025).
melanoma (2 papers, 2019 to 2021). A malignant, usually aggressive tumor composed of atypical, neoplastic melanocytes. "We found that the knockdown of RNA modification regulatory protein encoding genes (METTL4 and DNMT3A) inhibited the ability of melanoma cells to form colonies in soft agar." (PMID 31217906, 2019). "We also performed functional validation studies for DNMT3A and METTL4 and found that they are potentially important for melanoma growth." (PMID 31217906, 2019). "However, we also observed that both DNMT3A and METTL4 are significantly overexpressed in skin squamous cell carcinoma, skin basal cell carcinoma as well as in melanoma metastatic samples in Riker melanoma dataset set." (PMID 31217906, 2019). "The results obtained in both Riker and UALCAN datasets show that both DNMT3A and METTL4 expression in upregulated in metastatic melanoma samples and hence these genes may play an important role in melanoma growth and progression." (PMID 31217906, 2019). "Next, we asked if these RNA-modifying enzyme/proteins (METTL4 and DNMT3A) that are overexpressed in melanoma samples are necessary for its growth." (PMID 31217906, 2019). "Collectively, in this study, we investigated the epitranscriptomic landscape of melanoma using various publicly available database and identified DNMT3A and METTL4 as the most relevant potential regulators of melanoma growth." (PMID 31217906, 2019). "Based on this we infer that the upregulated expression of RNA modification regulatory proteins METTL4 and DNMT3A play a key role in melanoma initiation or progression." (PMID 31217906, 2019). "Our comprehensive analysis on the RNA modification regulatory proteins led us to conclude that METTL4 and DNMT3A are the candidates that showed consistent increase in the RNA as well as protein expression of melanoma samples using TCGA, Oncomine and The Human Protein Atlas data." (PMID 31217906, 2019). "Therefore, we functionally validated METTL4 and DNMT3A using shRNA-mediated knockdown and found that their knockdown in melanoma cells led to melanoma cells growth inhibition." (PMID 31217906, 2019). "However, when examined in Oncomine dataset we found only two genes (METTL4 and DNMT3A) were significantly overexpressed in melanoma samples versus normal skin samples and matched with the results of The Human Protein Atlas data." (PMID 31217906, 2019).
Obesity (2 papers, 2023 to 2024). Accumulation of substantial excess body fat. "We found that adipose Mettl3, Mettl4, and m6A levels were upregulated in obesity." (PMID 37526326, 2023).
renal cell carcinoma (2 papers, 2021 to 2025). "Further study has shown that METTL3, along with METTL4, METTL14, NCBP1, and WTAP, may interact to impact cell cycle, renal cell carcinoma, and pathways that are included in cancer and hence may influence CRC growth." (PMID 40177651, 2025).
anemia (1 paper, 2026). A reduction in the number of red blood cells, the amount of hemoglobin, and/or the volume of packed red blood cells. "While the knockout of METTL4 improved SP mass, and anemia, there were no significant changes concerning white blood cells and platelets." (PMID 40819104, 2026).
Anophthalmia (1 paper, 2021). Absence of the globe or eyeball. "Mettl4 KO mice studies showed anatomical defects including craniofacial dysmorphism and anophthalmia in KO mice as compared to wild type controls." (PMID 34452636, 2021).
bacterial Sepsis (1 paper, 2025). "Furthermore, NRF2 is involved in METTL4-mediated m6A methylation modification, thereby regulating mitochondrial homeostasis and cellular ferroptosis in bacterial Sepsis-Associated AECs." (PMID 40842982, 2025). "Targeting methylation-modifying enzymes, such as METTL3, METTL4, and DNMT1, provides a promising therapeutic strategy to regulate gene expression, alleviate AEC dysfunction, and slow the progression of bacterial Sepsis-Associated ALI." (PMID 40842982, 2025).
bladder cancer (1 paper, 2019). "Meanwhile, the inhibitory role of Mettl4 in bladder cancer sphere formation, invasion and tumor propagation was also confirmed in T24 cells." (PMID 31760940, 2019).
breast invasive carcinoma (1 paper, 2025). "METTL1, METTL3, METTL4, METTL5, METTL6 and METTL13 were associated with poor prognosis in various tumors including liver hepatocellular carcinoma (LIHC), breast invasive carcinoma (BRCA), and lung adenocarcinoma (LUAD)." (PMID 41194259, 2025).
colitis (1 paper, 2021). Inflammation of the colon. "METTL3 and METTL4-deficient T helper cells do not induce colitis as they cannot differentiate into pathogenic effector T cells." (PMID 35127705, 2021).
head and neck cancer (1 paper, 2022). A primary or metastatic malignant neoplasm affecting the head and neck. "METTL4 may serve as a target for future therapy against specific types of cancer (e.g., UTUC, head and neck cancer)." (PMID 36461076, 2022).
heart failure (1 paper, 2025). Inability of the heart to pump blood at an adequate rate to meet tissue metabolic requirements. "Beyond cytosine methylation, excessive N6-methyladenine (6mA) in mtDNA—mediated by methyltransferase-like protein 4 (METTL4)—impairs mitochondrial gene expression and contributes to heart failure." (PMID 41009042, 2025).
hepatoblastoma (1 paper, 2023). Hepatoblastoma (HB) is a malignant hepatic tumor and is the most common pediatric liver cancer. "Our group has previously reported that many genetic variants of genes encoding RNA m6A and m7G methyltransferase, demethylase, and m6A-reading proteins confer hepatoblastoma susceptibility, including METTL3, METTL4, AlkB homolog 5 (ALKBH5), FTO, YTHDC1, YTHDF1, WTAP, WDR4, and METTL1." (PMID 37531210, 2023).
hepatocellular carcinoma (1 paper, 2022). A malignant tumor that arises from hepatocytes. "A recent study on m6A in hepatocellular carcinoma (HCC) showed involvement of METTL4 in HCC tumor progression." (PMID 35806168, 2022).
Insulin resistance (1 paper, 2023). Increased resistance towards insulin, that is, diminished effectiveness of insulin in reducing blood glucose levels. "Knockdown of METTL4 led to downregulation and inactivation of the INSR pathway, thereby regulating the IRS-1/PI3K/AKT pathway to improve insulin resistance." (PMID 37998047, 2023).
metastatic melanoma (1 paper, 2019). A melanoma that has spread from its primary site to another anatomic site. "We observed that both METTL4 and DNMT3A were significantly upregulated in metastatic melanoma samples as compared to primary tissue." (PMID 31217906, 2019).
oncocytoma (1 paper, 2021). "Compared to normal renal tissue protein expression of all investigated methyltransferases was increased in oncocytoma (METTL3 P < .001, METTL4 P < 0,001, METTL14 P = .003, KIAA1429 P = .001, WTAP P = .001)." (PMID 35474700, 2021).
urothelial carcinoma (1 paper, 2024). A malignant neoplasm derived from the transitional epithelium of the urinary tract (urinary bladder, ureter, urethra, or renal pelvis). "In urothelial carcinoma, METTL4 could mediate hypoxia‐induced urothelial mesenchymal transformation and tumor metastasis." (PMID 39619978, 2024).
tumor (15 papers, 2019 to 2024). "Changes in environmental hypoxia mediated by METTL4 lead to the enrichment of 6mA in mammalian tumor cells, activating multiple metastasis-inducing genes and resulting in tumor metastasis." (PMID 39155349, 2024). "METTL4 is highly expressed in upper tract urothelial cancer and METTL4 induces nuclear 6 mA modification during tumor metastasis." (PMID 39289775, 2024). "To test the in vivo tumorigenic ability of METTL4, we showed that METTL4 overexpression increased the tumor volume of tumor cells from three different tumor cell lines." (PMID 36461076, 2022). "METTL4 mediates nuclear 6mA depositions and its overexpression in tumor cells induces the epithelial-mesenchymal transition (EMT) and tumor metastasis." (PMID 36461076, 2022). "This METTL4-mediated nuclear 6mA deposition induces tumor metastasis through activating multiple metastasis-inducing genes." (PMID 36461076, 2022). "The in vitro migration and invasion activity of tumor cells were induced by METTL4 overexpression in two cell lines." (PMID 36461076, 2022). "For example, one study found that METTL4 down-regulation led to m6A modification dysregulation, which was related to tumor metastasis and poor prognosis in HCC." (PMID 36401285, 2022). "Taken together, several METTL genes, including METTL1, METTL2A, METTL4, EEF1AKNMT, and METTL24, had relatively higher frequencies of genetic amplification, deletion, or mutation in various tumor types, notably LUAD, BRCA, and GBM." (PMID 34285249, 2021). "METTL4 is a type of m6A-modified RNA that regulates tumor progression by modifying RNA." (PMID 37088822, 2023). "We show that hypoxia results in enriched 6mA levels in mammalian tumor cells through METTL4." (PMID 36461076, 2022). "Therefore, METTL4-mediated nuclear 6mA deposition inside nucleus controls hypoxia-induced gene expression and tumor metastasis through activating multiple metastasis-inducing targets, identifying METTL4 as a therapeutic target for hypoxia-involved tumors." (PMID 36461076, 2022). "Knockdown of lncRNA RP11-390F4.3 abolishes METTL4-mediated tumor metastasis." (PMID 36461076, 2022). "In conclusion, the m6A methyltransferases METTL3, METTL14, WTAP, KIAA1429, and METTL4 are dysregulated in ccRCC and might act as tumor suppressor genes." (PMID 35474700, 2021). "Studies in mouse models have demonstrated that drugs targeting mt-DNA can slow tumor development without suppressing the growth of healthy cells, as METTL4 can cause cell arrest in the G1 phase or lead to chromosome alignment disorders, thereby controlling the cell cycle process." (PMID 39155349, 2024). "HIF-1α overexpression induced an increase in tumor volume in three different cell lines, and the HIF-1α-induced increase in tumor volume was abolished by knockdown of METTL4 using three different siRNA vectors." (PMID 36461076, 2022). "Here we show that hypoxia induces nuclear 6mA modification through a DNA methyltransferase, METTL4, in hypoxia-induced epithelial-mesenchymal transition (EMT) and tumor metastasis." (PMID 36461076, 2022). "RNA methylation could regulate the innate immunity of the body, and targeting these methylation regulatory molecules (such as METTL3, METTL4, and FTO) can directly enhance tumor immunotherapy." (PMID 38442004, 2024). "In contrast, increased tumor volume by METTL4 overexpression was significantly decreased under knockdown of lncRNA RP11-390F4.3 in two cell lines, indicating that the tumorigenic activity induced by METTL4 was mediated by lncRNA RP11-390F4.3." (PMID 36461076, 2022). "To determine the role of METTL4 in tumorigenesis, we tested the role of METTL4 in hypoxia-induced tumor progression since hypoxia/HIF-1α induces the epithelial-mesenchymal transition (EMT) and tumor metastasis." (PMID 36461076, 2022).
cancer (7 papers, 2018 to 2025). A tumor composed of atypical neoplastic, often pleomorphic cells that invade other tissues. "Collectively, these data suggest that METTL3, rather than ALKBH5 or METTL4, is responsible for m6A-triggered erastin-induced ferroptosis in cancer cells." (PMID 39800682, 2025). "Therefore, we believe that although METTL4 is related to ferroptosis, it does not play a role in erastin-induced ferroptosis in cancer cells, which differs from its role in hepatic stellate cells." (PMID 39800682, 2025). "Firstly, there were several cancer-related RNA modification regulators, such as m6Am regulators PCIF1 and METTL4, were not included in our analysis." (PMID 37007958, 2023).
METTL4 also shares sentences with these, for which no sentence is quoted: clear cell renal cell carcinoma (1 paper); embryonal carcinoma (1); Intellectual disability (1); kidney disease (1); lung adenocarcinoma (1); lung carcinoma (1); mastitis (1); osteoporosis (1); seminoma (1); skin basal cell carcinoma (1); skin squamous cell carcinoma (1); soft tissue sarcoma (1); tuberculosis (1).